FGFR1 (fibroblast growth factor receptor 1)
Diseases named in the same sentence as FGFR1 in open-access papers (continued):
Sharing a sentence is not in itself a finding about the gene and the disease.
tumor (continued). "Statistical analysis revealed increased expression of FGFR1 neighboring genes on the 8p12 amplicon (BAG4, LSM1 and WHSC1L1) in FGFR1 amplified tumours, suggesting a broad rather than focal amplicon and raises the potential for codependencies." (PMID 26905262, 2016). "While the phase II study EAY131 led by Gong and colleagues, which enrolled 18 patients with tumor FGFR 1-4 amplification to receive erdafitinib and included 9 patients with BC did not meet its primary endpoint, with only one patient with FGFR1-amplified BC showing prolonged survival." (PMID 39040443, 2024). "Because methylation array tumor clustering is not feasible in such a large cohort, our approach to select cases by histology diagnosis, does not completely exclude cases with potential FGFR1-TACC1 fusions and FGFR1-TKD tandem duplication." (PMID 35018490, 2022). "We found that FGFR1 silencing significantly increased the sensitivity of MDA-MB-231-R cells to IGF-Trap treatment in vivo, although it could not completely inhibit tumor growth, over time." (PMID 33916323, 2021). "Notably, one FGFR1-amplified case (patient 13) and one FGFR2-amplified case (patient 4) showed high-level amplification in the smaller tumour rather than the largest tumour." (PMID 31929516, 2020). "While the detection of an FGFR1 alteration in a LGG/MNGT tumor of uncertain subtype may not aid in differential diagnosis between PA, DNT and RGNT, it may help to further narrow the differential diagnosis and exclude certain tumor entities, such as DA and PXA." (PMID 35018490, 2022). "Using patient demographics, tumor characteristics, and CGP, we show that GIST lacking alterations in canonical genes occur in younger patients, frequently metastasize to lymph nodes, and most contain deleterious genomic alterations, including gene fusions involving FGFR1 and NTRK3." (PMID 27974047, 2016). "Even without expression of ectopic FGFR1, these cells could undergo FGF2-induced EMT, suggesting that if FGF was present in the tissue microenvironment in vivo, the tumours from which these cell lines were established may have expressed an FGFR-dependent EMT phenotype." (PMID 22701738, 2012).
cancer (575 papers, 1992 to 2026). A tumor composed of atypical neoplastic, often pleomorphic cells that invade other tissues. "Fibroblast growth factor receptor 1 (FGFR1), implicated in various cancer types, has been extensively investigated as a target for antitumor therapy." (PMID 40848289, 2025). "Activating mutations of FGFR1–4 occur in a variety of human cancer and they can involve activating point mutations (SNV), genetic fusion and genetic amplification." (PMID 41202566, 2025). "A relevant study demonstrated that fibroblast growth factor receptor 1 (FGFR1) is encoded by circFGFR1, which is downregulated in cancer." (PMID 40723354, 2025). "FGF2 from cancer-associated fibroblasts stimulates the growth and progression of human BC cells through FGFR1 signaling." (PMID 40547857, 2025). "In light of FGFR1’s pathogenic role, several therapeutic agents targeting FGFR1 have been developed for cancers with FGFR1 dysregulation." (PMID 40510030, 2025). "In cancers, it has been demonstrated that FGFR1 is deregulated by amplification, point mutation, or translocation." (PMID 39942770, 2025). "Conversely, selective FGFR inhibitors, such as erdafitinib, have entered clinical practice to suppress aberrant FGFR1 activity in cancers characterized by receptor overexpression, mutation, or gene amplification." (PMID 41226200, 2025). "Members of the fibroblast growth factor receptor family, including FGFR1, frequently undergo genomic alterations such as mutations, amplifications, and gene fusions across various cancer types." (PMID 40934169, 2025). "In cancer, FGFR1 amplification is associated with aggressive behavior and resistance to therapy, making FGFR1 a critical target." (PMID 41226200, 2025). "Dysregulation or overexpression of FGFR1 has been implicated in oncogenesis, particularly in cancers such as breast and lung carcinoma." (PMID 41226200, 2025). "This suggests that alterations in FGFR1 are not only likely to contribute to the progression of these cancers but are also closely linked to poor prognosis." (PMID 39590377, 2024). "FGFR1 amplification is common in HR+ cancers, HER2+ cancers and TNBC, and is associated with poor prognosis." (PMID 39138146, 2024). "These mutation sites are mainly located in the kinase domain of FGFR1 and are associated with abnormal activation of FGFR1 and various diseases, including cancer." (PMID 38831455, 2024). "FGFR1, the gene encoding fibroblast growth factor receptor 1, is emerging as a therapeutic and predictive biomarker in various cancer types, including HNSCC." (PMID 38129938, 2023). "Specifically, the αAMTN-dFGF2V1V2-MMAE conjugate effectively kills cancer cells with high levels of FGFR1 while exhibiting minimal toxicity towards FGFR1-deficient cells." (PMID 37373291, 2023). "Targeting fibroblast growth factor receptor 1 (FGFR1) is a promising therapeutic strategy for various cancers associated with alterations in the FGFR1 gene." (PMID 37373291, 2023). "Hematopoietic progenitor kinase 1 (HPK1) and fibroblast growth factor receptor (FGFR1), which are implicated in a variety of cancer types, have been extensively studied for antitumor therapy." (PMID 37989998, 2023). "Inferred CNV from our high resolution single nucleus analysis identifies Chr8p loss (containing NKX3–1, BMP1, FGFR1 genes and multiple microRNAs) as one of the earliest genetic events in prostate tumorigenesis, shared by >43% of cancer cells in GS6 tumors." (PMID 37327786, 2023). "High expression levels of FGFR1 are linked to poor survival and FGFR1 is a regulator of cancer stem cells and therapy resistance in GBM." (PMID 37579831, 2023). "In the context of cancer, aberrant signalling of FGF10 through FGFR2 IIIb, and to a lesser extent FGFR1 IIIb, has been implicated in a range of cancers." (PMID 37130917, 2023).
cancer (continued). "Aberrant expression of FGFR1 due to gene amplification, chromosome rearrangement, point mutation, and epigenetic deregulations, have been reported in various cancers." (PMID 37993879, 2023). "We have recently shown that dual inhibition of PLK1 and FGFR1 has synergistic anticancer effects in KRAS-mutant cancer cells, as FGFR1 and PLK1 cooperate control the metabolic stress associated with KRAS mutation." (PMID 36483040, 2022). "FGFR1 is a tyrosine kinase receptor whose inhibitors have been used extensively in Phase I/II clinical trials for treatment in cancers presenting FGFR1 mutation." (PMID 35742955, 2022). "The K656E mutation lies within the “YYKK” activation loop sequence in FGFR1 and is an activating mutation found in cancers as well as developmental disorders." (PMID 35574218, 2022). "Mutations in the FGFR1 pathway are frequently observed in cancer and it has been reported that FGFR1 is strongly expressed in PC in association with poor outcomes." (PMID 35141164, 2022). "In contrast, some studies showed that FGFR1 expression was linked to less aggressive types of cancers." (PMID 35683481, 2022). "Since FGFR1 amplifications have been associated with other cancers, we analyzed copy number variations in a public dataset of 381 NBs." (PMID 35488346, 2022). "All four types of FGFR (FGFR1–4) have been associated with specific cancer types, and FGFR2 alteration has been most widely found in GC." (PMID 36292044, 2022). "Aberrations of FGFR1–4 genes are associated with a broad range of developmental disorders, such as craniosynostosis and dwarfing syndromes, and with cancers." (PMID 35402233, 2022). "FGFR1 amplification is also common in ER-positive carcinomas and has been associated with increased grade and proliferation index." (PMID 35590107, 2022). "The strongest evidence by far indicates that FGFR1 has malignancy-promoting effects and FGFR1 signaling is linked to cancer stemness, invasion and radioresistance in GB." (PMID 34209513, 2021). "Due to resistance mediated by target mutation or bypass signal activation, treatment of FGFR1 amplified cancers with FGFR inhibitors is currently unsatisfactory." (PMID 34114373, 2021). "In summary, broad analyses aimed at determining the frequency and type of somatic SNVs in FGFR1–4 in human cancer have revealed a diverse spectrum of variants spanning the entire protein sequence." (PMID 33268819, 2021). "Formation of N-cadherin complexes with FGFR1 in cancer cells causes decreased internalization and lysosomal degradation of FGFR1 and sustained receptor signaling via MAPKs." (PMID 33352931, 2020). "This resulting data give additional clues to the underlying biology of DESNT cancer, including associations with genes altered in ductal breast cancer, in stem cells and during FGFR1 signalling." (PMID 32203215, 2020). "Of these, 29 are associated with activation of EGFR and/or FGFR1 gene products in varying types of cancer (FDR qvalue = 4.68e− 15 and 3.74e− 15, MutsigDB)." (PMID 32209086, 2020). "In a study of almost 5000 various cancers by next-generation sequencing, FGFR alterations were found in 7.1% of the cancers, with the majority being gene amplification (mostly in FGFR1), followed by mutations and rearrangements." (PMID 32245111, 2020). "The gene encoding FGFR1 is located on chromosome 8p11.23 and encodes tyrosine kinase family, which plays crucial roles in cancer development." (PMID 32326908, 2020). "FGFR1 amplification has been suggested as an oncogenic driver mutation in tobacco-associated cancers of the aerodigestive tract." (PMID 32326908, 2020). "The strongest evidence by far indicates that FGFR1 is an important contributor to poor outcome in GBM, and FGFR1 signaling is linked to cancer stemness, invasion, and radioresistance." (PMID 31337028, 2019).
cancer (continued). "Whole genome sequencing data of multiple types of human cancers showed that amplifications, mutations and rearrangements of FGFR1/2/3/4 were detected in 3.5%, 1.5%, 2.0%, and 0.5%, respectively." (PMID 30111373, 2018). "The malfunction in the RTK-dependent signaling pathways (including FGFR1 dependent signaling cascades) is associated with numerous diseases, including cancer." (PMID 28769084, 2017). "Aberrant activation of FGFR1 signaling, resulting from FGFR1 amplification or mutation, has been increasingly found to be a driving factor in tumorigenesis for multiple types of cancers." (PMID 27391347, 2016). "N540 FGFR3 mutations in bone dysplasia reflect the overall picture of FGFR1-4 mutations in cancer with the replacement N540K being the most frequently observed." (PMID 26992226, 2016). "We also found a strong upregulation of the cancer associated gene FGFR1 and several FGF ligands, all of them acting within the pathways of cancer and regulation of actin cytoskeleton." (PMID 26998479, 2015). "Active mutations of FGFR2 or FGFR3 are common in various cancers, whereas the oncogenic impetus of FGFR1 results mainly from either gene amplification or overexpression of wild-type receptor." (PMID 26201468, 2015). "PKM2 is known to interact with a variety of biological molecules such as A-Raf, FGFR-1 and Jak-2 mutant and is also implicated in cancer metabolism." (PMID 23382852, 2013). "In summary, our gene expression analysis using a focused cancer-associated gene set supported previous data on AR and uncovered the association of FGFR1 in CRPC." (PMID 21952621, 2011). "Indeed, given that phosphate overload is associated with dysregulated renal function and cancer cell growth, research should investigate if phosphate overload is similarly associated with dysregulation of the FGFR1 pathway in cancer." (PMID 40643473, 2025). "Impaired FGFR1 signaling is associated with more than 10 different cancer diagnoses." (PMID 39759879, 2025). "In childhood and adolescent cancers, mutations, fusions, and amplifications of FGFR1–4 are all relatively common, particularly in low-grade neuroepithelial tumors where they are significantly more prevalent than in adults, suggesting developmental stage-related differences in oncogenic mechanisms." (PMID 41514604, 2025). "As over‐activity of FGFR1 is implicated with cancer, effective inhibitors are in demand." (PMID 34038603, 2025). "Similar to other targeted therapies, cancer cells may develop mutations in the FGFR1 pathway or activate alternative signaling pathways to bypass FGFR1 inhibition, ultimately leading to therapeutic resistance." (PMID 40547805, 2025). "In addition, research has shown that tumors with FGFR1, a receptor tyrosine kinase that has been implicated in various cancers, have worse differentiation and are more likely to spread, whereas tumors lacking it have smaller and more differentiated phenotypes." (PMID 40429793, 2025). "We have recently demonstrated that N-glycans of FGFR1 are recognized by a precise set of extracellular galectins, secreted and intracellular multivalent lectins implicated in a plethora of cellular processes and altered in immune responses and cancers." (PMID 38750548, 2024). "Of the kinase inhibitor gene targets evaluated, high pre-treatment PIKFYVE, KDR, NTRK1, IKBKB, FLT1, or FGFR1 expression was each associated with lower odds of achieving CR when controlling for cancer type, biopsy site, age at the time of treatment initiation, and ICB agent." (PMID 38464258, 2024). "Since galectins and FGFR1 are strongly implicated in cancers, our data might contribute to the development of novel anti-cancer therapeutic strategies." (PMID 38750548, 2024). "DeAc-KLF5 upregulates CX3CR1 to enhance FGFR1 activation in PTEN-deficient cancer cells." (PMID 38781024, 2024).
cancer (continued). "FGFR1, one of the upregulated genes, encodes a protein that belongs to the family of the fibroblast growth factor receptor, which is a key factor in many cancer-related pathways, such as the MAPK signaling pathway, Ras signaling pathway, and PI3K-Akt signaling pathway." (PMID 37546388, 2023). "High expression of ANK1 and FGFR1 are associated with poor outcomes in several cancer types." (PMID 37182141, 2023). "In addition, we found the somatic mutation N546K, the most recurrent point mutation of FGFR1 in all cancers and already reported in NB, in one out of 19 matched primary and recurrent tumors." (PMID 35488346, 2022). "In addition to the already-known targets, we further identified relevant cancer-associated genes; such as, FGFR1, VEGFA, WNT9A, and FZD4." (PMID 35132075, 2022). "Furthermore, FGFR1 mutations in cancer tissues have been associated with spontaneous intratumoral hemorrhage, as observed in our patient." (PMID 35778969, 2022). "Importantly, FGFR1-induced palbociclib resistance was associated with promotion of cancer cell stemness and the upregulation of Wnt/β-catenin signaling." (PMID 34831231, 2021). "Like other RTKs, FGFR1-4 have been implicated in cancers arising from nearly all tissue types." (PMID 34068954, 2021). "Mutations and translocations of FGFR1-4 are also identified in cancer." (PMID 34068954, 2021). "Importantly, FGFR1 overexpression or miR-15a-5p downregulation abrogated the anti-cancer activities of CERS6-AS1 deficiency on the malignant characteristics of PDAC cells." (PMID 33581689, 2021). "Moreover, NRP2 and FGFR1 expressions were explicitly associated with cancer survival in bladder cancer." (PMID 32695477, 2020). "Although the precise reason for this discrepancy in different cancer types is unclear, it could probably be due to the different pathogenic roles of FGFR1 in various cancers." (PMID 32171280, 2020). "Activation of FGFR1 has been shown linked with a large body of human cancers." (PMID 31138759, 2019). "Abnormal activation of the FGFR1-mediated signaling pathway can be caused by translocation, point mutation and amplification of the FGFR1 gene, hence leading to malignant transformation and cancer progression." (PMID 30866584, 2019). "Several studies have implicated that overexpression of FGFR1β is associated with tumorigenesis and poor survival in multiple tumors, while FGFR1α, on the other hand, governs cell differentiation in normal tissues, suggesting that the two FGFR1 variants have different effects on cancer cells." (PMID 30713601, 2019). "FGFR1 expression was associated mainly with luminal cancers, particularly luminal B subtype (23.5%; p < 0.001), and it also showed adverse prognostic impact on luminal A cancers." (PMID 26673008, 2016). "Interestingly, it has been shown that FGFR1 without the signal peptide accumulates in the cytosol and the nucleus, and that nuclear FGFR1 has been associated with invasive cancer cells." (PMID 27685995, 2016). "Thus, based on our strategy, the chromosome 8: 37.5–43.1Mb region is more likely to harbor cancer drivers, which indeed encodes known driver gene FGFR1." (PMID 26030765, 2015). "Potential perturbation of the INFS mechanism, brought about by gene binding of truncated FGFR1, could underlie pathological gene reprogramming in cancer cells." (PMID 23874817, 2013). "Additionally, it remains unclear whether FGFR1 amplification represents the underlying molecular cause as a driver of cancer, or simply exists as “passenger” event within the overall mutational profile of cancer." (PMID 35402233, 2022). "A family of proteins involved in many cancers, known to regulate cell cycle, associated with stem cells and drug resistance and whose expressions have been variously affected by FGFR1 silencing, has particularly attracted our attention, the Forkhead box (FOX) family." (PMID 30167084, 2018).